S1PR1 (sphingosine-1-phosphate receptor 1)
Diseases named in the same sentence as S1PR1 in open-access papers (continued):
Sharing a sentence is not in itself a finding about the gene and the disease.
melanoma (15 papers, 2016 to 2024). A malignant, usually aggressive tumor composed of atypical, neoplastic melanocytes. "Altogether, these results suggest that S1P produced by melanoma cells stimulates macrophage migration in a S1PR1-dependent manner." (PMID 27708249, 2016). "In vitro, our findings demonstrate that S1P produced by melanoma SK1 acts as a potent chemoattractant for macrophages in a S1PR1-dependent manner." (PMID 27708249, 2016). "The activation of S1PR1 also increases myosin light chain phosphorylation that tightens the junctions between the endothelial cells forming the microvessel wall, which inhibits lung metastasis by up to 80% in a melanoma metastasis animal model." (PMID 38275815, 2024). "Additionally, treatment of mice with the S1P receptor modulator FTY720, which renders cells unresponsive to S1P activation by sequestering S1PR1 intracellularly, reduced melanoma progression by inhibiting tumor vascularization." (PMID 27708249, 2016). "Indeed, stimulation or inhibition of S1P-induced migration in melanoma cells depends on expression of S1PR1 or S1PR2, respectively." (PMID 27800303, 2016). "Since S1PR1, 2 and 3 are expressed by BMDM, we next examined whether S1PR1 and S1PR3, which are known to promote cell migration, are implicated in BMDM migration upon incubation with melanoma CM." (PMID 27708249, 2016). "Moreover, we have recently demonstrated that activation of NF-κB by extracellular S1P in melanoma cells involved both S1PR1 and S1PR2 and was inversely correlated with the expression of the actin-binding protein FlnA." (PMID 27800303, 2016). "The connection between S1PR1 and STAT3 activation was fundamental in lymphoma, adenocarcinoma, melanoma, breast, and prostate cancers, and targeting S1PR1 to decrease expression of STAT3-regulated genes resulted in inhibition of tumor progression." (PMID 36672428, 2023). "A pivotal study established a direct relationship between S1PR1 and STAT3 expression in distinct tumors, including lymphoma, adenocarcinoma, melanoma, breast, and prostate cancer." (PMID 27800303, 2016).
Stroke (15 papers, 2015 to 2025). Sudden impairment of blood flow to a part of the brain due to occlusion or rupture of an artery to the brain. "The possible involvement of S1P in the regulation of the molecular mechanisms potentially associated with stroke came from the evidence that levels of S1PR1, which has recently been identified as a positional candidate gene for salt-sensitivity in SHRSP, increased in the SHRSR tissues." (PMID 33917593, 2021). "In this review, we summarized the effect of S1PR1 modulators on brain injury and provided an overview of the use of S1PR1 modulators for treating MS, stroke, NDDs, and TBI." (PMID 40438602, 2025). "Moreover, S1P has recently emerged as an integral player in coordinating lymphatic transport and maintaining endothelial cell barrier integrity by activating multiple cognate receptors, such as S1PR1, to resist stroke injury." (PMID 36698123, 2023). "Endothelium-specific S1PR1-knockout mice exhibit impaired blood-brain-barrier integrity and increased adhesion molecule expressions in a middle cerebral artery occlusion-induced stroke model." (PMID 34222276, 2021). "Expression of S1PR1 was increased in both spontaneously hypertensive rats that are stroke resistant (SHSR) and spontaneously hypertensive rats that are stroke prone (SHSP) when compared to normotensive Wistar Kyoto rats." (PMID 35457062, 2022). "Increased Smyd2 impairs S1PR1 formation and induces S1PR3 production, which is detrimental to TJs and BBB dysfunction after stroke." (PMID 35297562, 2022). "Therefore, targeting of this novel pathway would have a potential advantage compared with targeting S1PR1 since it could lead to neurovascular protection without compromising immune function, which could be especially beneficial for stroke patients." (PMID 26243335, 2015).
myocardial infarction (14 papers, 2016 to 2025). Gross necrosis of the myocardium, as a result of interruption of the blood supply to the area, as in coronary thrombosis. "In addition, they found that the upregulation of SphK1 and S1PR1 caused an increase in cardiac S1P after myocardial infarction, while the SphK1 inhibitor inhibited S1P and improved cardiac insufficiency." (PMID 37238688, 2023). "S1PR1 activation can improve cardiac function and myocardial healing after myocardial infarction in mice." (PMID 40860187, 2025). "This study suggests a promising CM-targeted therapy for myocardial infarction and heart failure through the S1PR1 signal pathway." (PMID 39816679, 2025). "This CM-specific overexpression of S1pr1 significantly promoted cardiomyocyte proliferation and improved cardiac functions after myocardial infarction in adult mice, offering a promising cell-specific gene delivery system for treating heart failure." (PMID 39816679, 2025). "This study suggests a promising CM-targeted therapy for myocardial infarction and heart failure by promoting cardiac regeneration through the S1PR1 signaling pathway." (PMID 39816679, 2025). "Another study confirmed that the SphK1/S1P/S1PR1 signaling pathway activates the proinflammatory response after myocardial infarction." (PMID 37238688, 2023). "In this report, our data showed that the expression of S1pr1 in LECs was significantly reduced in hearts after myocardial infarction." (PMID 36003911, 2022). "Conversely, significant increases in cardiac S1P, SphK1 and S1PR1 are observed in postmyocardial infarction (MI) associated with the proinflammatory response, and inhibition of this inflammatory pathway may benefit patients with MI." (PMID 33003377, 2020). "Moreover, CM-targeted gene delivery of S1pr1 to achieve CM-specific S1PR1 overexpression significantly boosted cardiomyocyte proliferation and improved cardiac functions after myocardial infarction in adult mice." (PMID 39816679, 2025). "Moreover, CM-targeted gene delivery of S1pr1 to achieve CM-specific S1PR1 overexpression in vivo significantly enhanced cardiomyocyte proliferation and improved cardiac function following myocardial infarction in adult mice." (PMID 39816679, 2025). "Our further in vivo experiments showed that a reduced expression of S1pr1 in LECs deteriorated pathological ventricular remodeling and worsened cardiac dysfunction after myocardial infarction, suggesting that LEC-S1pr1 exerts a key role in improving post-MI cardiac remodeling and functions." (PMID 36003911, 2022). "Furthermore, we showed that cardiac endothelial cell-expressing S1PR1 promoted reparative macrophage proliferation, contributing to the protective effects of SEW2871 on myocardial infarction." (PMID 39816679, 2025).
COVID-19 (12 papers, 2020 to 2025). A disease caused by infection with severe acute respiratory syndrome coronavirus 2. "In ECs obtained from deceased patients who had COVID-19, the arterial subtype also predominantly expressed F2R, S1PR1, and NOS3." (PMID 39066212, 2024). "One of the potential positive effects of FTY720-P antagonism of S1PR1 in COVID-19 therapy is the curbing of hyperinflammation or “the cytokine storm”." (PMID 33003377, 2020). "Other potential beneficial effects of FTY720 agonism on S1PR1,3,4,5 in COVID-19 treatment include the regulation of thrombopoiesis through S1PR4 activation." (PMID 33003377, 2020). "In liver autopsy samples from patients who died because of COVID-19 complications, PC activation signaling receptors were significantly decreased compared with control as follows: 2.7-fold for S1PR1, 2.5-fold for F2R and 1.7-fold for THBD (p < 0.001), and less than 5% of cells expressed these genes." (PMID 36560757, 2022). "Thus, the therapeutic relevance of FTY720 in COVID-19 is complex, probably due to its antagonistic effect on S1PR1 leading to the degradation of this receptor and inhibition of S1PR1-mediated vascular protection, while it can still enhance the EC barrier via a novel S1PR1-independent mechanism." (PMID 37685894, 2023). "The results revealed various diseases from the common DEGs of AKI, CKD, and COVID-19, which include DUSP6, NRIP1, TNFAIP8, S1PR1, and TANK." (PMID 37026010, 2023). "We found that PROC, S1PR1, and THBD were downregulated in the nasal epithelium of patients with COVID-19." (PMID 36560757, 2022). "S1PR1 expression was localized to submucosal gland like structures in both control and COVID-19+ autopsies with no notable difference in expression." (PMID 37868972, 2023). "Our evaluations of S1PR1 and S1PR2 suggest that the SK1 induction and downstream signaling may have involved S1PR2 in COVID-19+ autopsies and not S1PR1." (PMID 37868972, 2023).
lymphoma (12 papers, 2014 to 2024). A malignant (clonal) proliferation of B- lymphocytes or T- lymphocytes which involves the lymph nodes, bone marrow and/or extranodal sites. "(F) Flow cytometric analysis of S1PR1 surface expression on WEHI231 lymphoma cells transduced with S1PR1 and CD69 wild-type and mutant constructs as indicated." (PMID 37039481, 2023). "One of the upregulated miRNAs was specifically associated with the repression of S1PR1, hinting to a role for low S1PR1 in lymphoma." (PMID 36361536, 2022). "IHC of S1PR1 showed the positive staining in most lymphoma cells." (PMID 36600310, 2023). "Blocking S1PR1 can retain lymphoma cells in lymphoid organs because of an egress function defect." (PMID 31534132, 2019). "At present, only a few studies on S1PR1 in malignant lymphoma are available." (PMID 25472725, 2014). "S1PR1/S1PR3-YAP and S1P-ALOX15 signaling have also recently been shown to contribute to aggressive behavior in obesity-related lymphomas." (PMID 38339325, 2024). "Three S1PR inhibitors (W146 for S1PR1, CAY10444 for S1PR3, and FTY720 for S1PR1–5) were selected to demonstrate the hypothesis that S1P signaling could mediate the HIPPO pathway in lymphoma cells." (PMID 36600310, 2023). "Finally, leukaemic lymphomas (6 FL, 5 MCL and 2 MZL) were characterised by aberrant expression of the egress receptor S1PR1 and low expression of molecules required for tissue entry/retention." (PMID 25938000, 2015). "In a previous study by Liu, STAT3 was co-localized with S1PR1 in the tumor cells of a few ABC DLBCL tissues, and the inhibition of S1PR1 with FTY720 or S1PR1 shRNA successfully suppressed STAT3 activity and tumor cell growth in vitro and in an in vivo murine lymphoma model." (PMID 25472725, 2014).
Sepsis (12 papers, 2012 to 2026). Sepsis is defined as life-threatening organ dysfunction caused by a dysregulated host response to infection. "A study demonstrated that PF-543 alleviated lung injury caused by sepsis in acute ethanol intoxication rats by suppressing the SPHK1/S1P/S1PR1 signaling pathway." (PMID 36361531, 2022). "S1PR1-associated biomarkers could predict the survival of patients with sepsis using gene expression profiles of peripheral blood." (PMID 37233274, 2023). "The increased brain uptake of [18F]TZ4877 could be resulted from increased brain S1PR1 expression or caused by sepsis-induced BBB breakdown." (PMID 34934406, 2021). "For example, pharmacological targeting of S1PR1 can improve renal microcirculation during sepsis in mice." (PMID 34722589, 2021). "In addition, S1PR1 is considered to play a critical role in the development of sepsis; for example, S1PR1-specific agonist SEW2871 can successfully protect against renal injury in a sepsis model." (PMID 34934406, 2021). "Moreover, the simulation of the sepsis by intraperitoneal LPS injection perturbs sphingosine metabolism in brain microvessels with a net decrease of S1PR1 levels, thus linking alterations of sphingolipid metabolism to the pathogenesis of septic encephalopathy." (PMID 31091708, 2019). "In future, APC mutants that lack anticoagulant properties but still enable sphingosine 1 phosphate receptor 1 dependent activation of PAR-1 will be of special clinical interest as they have been shown to reduce sepsis-induced in mice but do not predispose to bleeding complications." (PMID 22518344, 2012). "Among S1PRs 1–5, we found both S1PR1 and S1PR3-related gene signature are capable of predicting the survival of patients with sepsis." (PMID 33549110, 2021). "S1PR1 and S1PR3 play a diverse role and belongs to different signaling pathways in sepsis progression." (PMID 33549110, 2021). "In general, S1PR1 and S1PR3 gene signature have diverse molecular mechanisms in the pathology of sepsis, so we decided to publish them separately." (PMID 33549110, 2021).
systemic lupus erythematosus (12 papers, 2015 to 2024). An autoimmune multi-organ disease typically associated with vasculopathy and autoantibody production. "In conclusion, we presented that the deletion of Mir223 exacerbated the lupus phenotypes associated with increased population of S1PR1+CD4+ T cells and their enhanced infiltration in inflamed kidney tissues." (PMID 33574820, 2020). "Unexpectedly, the deletion of Mir223 exacerbated the lupus phenotypes associated with increased population of S1PR1+CD4+ T in spleen and the enhanced infiltration of S1PR1+CD4+ T cells in inflamed kidney tissues, suggesting compensatory role of Mir223 in the pathogenesis of lupus nephritis." (PMID 33574820, 2020). "Consistent with our results, in systemic lupus erythematosus, S1PR1 is expressed less in peripheral blood mononuclear cells (PBMCs) of patients than in healthy controls." (PMID 31968593, 2020). "In the present study, we investigated the roles of miR-223-3p and S1pr1 mRNA in the MRL/lpr lupus-prone mice." (PMID 33574820, 2020). "Here, we demonstrated that miR-223-3p plays a critical role in the regulation of T cell circulation and apoptosis by targeting S1PR1 in lupus prone mouse." (PMID 33574820, 2020). "Regulating T cell circulation by targeting S1PR1 in lupus-prone mice." (PMID 39835138, 2024).
ulcerative colitis (12 papers, 2018 to 2025). An inflammatory bowel disease involving the mucosal surface of the large intestine and rectum. "Findings in mice were recapitulated in ulcerative colitis patients treated with the S1PR1 antagonist ozanimod, and the loss of naive T cells limited B cell responses." (PMID 38194271, 2024). "Findings using genetic models were recapitulated in mice treated with the drug fingolimod (FTY720), which targets S1PR1, and in ulcerative colitis patients treated with the drug ozanimod, also an S1PR1 modulator." (PMID 38194271, 2024). "CBP-307 is a highly potent and selective S1PR1 modulator currently being evaluated in a global phase 2 clinical study of moderate-to-severe ulcerative colitis and Crohn’s disease." (PMID 38482014, 2024). "Ozanimod, a small molecule modulator of S1PR1/5, has shown efficacy in clinical trials in relapsing multiple sclerosis and ulcerative colitis." (PMID 35782389, 2022). "Targeting S1PR1 with small molecule drugs has proven therapeutic utility in the treatment of relapsing multiple sclerosis (MS) and ulcerative colitis." (PMID 29608575, 2018). "In addition to MS, new applications, such as treatment of ulcerative colitis, have been proposed for the S1PR1 agonists, ozanimod and etrasimod." (PMID 39030171, 2024). "Ozanimod, a sphingosine 1-phosphate receptor 1 and 5 modulator, was approved as a disease-modifying therapy for active relapsing-remitting multiple sclerosis (RRMS) in 2020 and for active ulcerative colitis in 2021." (PMID 35832177, 2022).
viral infection (12 papers, 2013 to 2025). "S1PR1 is involved in the regulation of the MAPK and NLRP3 signaling pathways associated with the production of inflammatory factors caused by viral infection, indicating that S1PR1 may regulate inflammatory responses through the MAPK and NLRP3 signaling pathways." (PMID 35854395, 2022). "For example, the S1PR1 (sphingosine-1-phosphate receptor 1) gene was identified on chromosome 8 and is known to encode a lipid regulator that is involved in processes such as immune response and to contribute to immune response to viral infections, especially influenza infection." (PMID 34503452, 2021). "Increasing evidence indicates that S1PR1 expression is tightly correlated with the inflammatory response to infectious diseases such as viral infections, bacterial infections, protozoan infection, and fungal infection." (PMID 34934406, 2021). "Extracellular S1P binding to S1PR1 also plays a dual role in inflammation by the activation of intracellular inflammatory signalling pathways during viral infections." (PMID 33003377, 2020). "HPMECs were transfected with the plasmid expressing HA-tagged S1PR1 or with the S1PR1-specific siRNA, prior to the viral infection." (PMID 30304001, 2018). "We also proved infected HPMEC treated with CYM5442 produced decreased levels of ICAM1 compared to infected cells treated with vehicle, suggesting the activation of S1PR1 is an important regulatory pathway for inflammation in lungs induced by viral infection." (PMID 28399143, 2017). "A S1PR1 agonist CYM5442 was added to the culture media to assess CYM5442’s inhibitory effects during virus infection." (PMID 28399143, 2017). "In agreement with a previous paper, we observed HPMEC expressed S1PR1 at both the mRNA and protein levels, and viral infection increased the expression of S1PR1." (PMID 28399143, 2017). "Interestingly, there has been a dearth of studies examining S1PR1 expression and inflammation in other viral infections." (PMID 37762169, 2023). "Viral infection can induce the expression of S1PR1 in endothelial cells." (PMID 35854395, 2022). "This indicated a crucial role of S1PR1 in influenza infection and suggested that S1PR1 signaling may be important in the immune response to other viral infections as well." (PMID 24073762, 2013). "Further research on S1PR1 signaling may enhance research and development of anti-influenza drugs and provide new opportunities for prevention and treatment of other human viral diseases." (PMID 24073762, 2013). "The possibility of crosstalk between ACE2 and S1PR1 or other S1PR subtypes, specifically expressed in different cell types might contribute to extend individual diversity of virus infection response." (PMID 32942748, 2020). "In agreement with these publications, we demonstrated here the specific S1PR1 agonist CYM5442 decreased the upregulated ICAM1 in endothelial cells upon H1N1 virus infection, indicating the regulatory functions of S1PR1 in endothelial cells also apply in virus infection." (PMID 28399143, 2017). "Activation of S1PR1 using a S1PR1 agonist, CYM-5442, was protective against viral challenge in control mice, but not in the S1PR1-ECKO mice, highlighting the importance of S1PR1 signalling in the control of viral infection." (PMID 33003377, 2020).